GSDME (gasdermin E)
Diseases named in the same sentence as GSDME in open-access papers (continued):
Sharing a sentence is not in itself a finding about the gene and the disease.
non-small cell lung carcinoma (6 papers, 2021 to 2025). A group of at least three distinct histological types of lung cancer, including non-small cell squamous cell carcinoma, adenocarcinoma, and large cell carcinoma. "L 50377 44, piperlongumine 45, and AZD 4635 46 are pyridine-containing molecules with pyroptotic activities that exert their effects on non-small cell lung cancer (NSCLC) by activating GSDME." (PMID 39316325, 2025). "The GSDME-EGFR interaction plays an important role in non-small cell lung cancer development, reveal a previously unrecognized link between GSDME and EGFR stability and offer new insight into cancer pathogenesis." (PMID 37085908, 2023). "GSDME expression is closely related to cisplatin sensitivity in non-small cell lung cancer." (PMID 38169676, 2024). "GSDME-EGFR interaction was involved in the development of non-small cell lung cancer, which could open the horizon of cancer pathogenesis." (PMID 39607202, 2024). "GSDME depletion reduced the proliferation of non-small cell lung cancer cells in vitro." (PMID 37085908, 2023).
pancreatic cancer (6 papers, 2022 to 2026). "Together, these results suggest that GSDME is required for the orthotopic growth of pancreatic tumours." (PMID 35292781, 2022). "We identified GSDMB, GSDMD, and GSDME as the top three genes expressed in pancreatic cancer." (PMID 39358349, 2024). "Given that GSDMB and GSDME are also highly expressed in pancreatic cancer." (PMID 39358349, 2024). "Notably, GSDME was localized in the nucleus in pancreatic tumour cells, which was enhanced by the presence of trypsin and chymotrypsin." (PMID 35292781, 2022). "Notably, GSDME is typically down-regulated in pancreatic tumor tissues due to promoter hypermethylation in others work, while EV-U could increase the GSDME expression and further enhance the cellular pyroptosis response." (PMID 40604924, 2025).
prostate carcinoma (6 papers, 2020 to 2025). A carcinoma that arises from epithelial cells of the prostate gland. "Prior research has indicated that CDC20 downregulation can bolster an anti-tumor immune response of prostate cancer by facilitating CD8 lymphocyte infiltration dependent on GSDME." (PMID 40688701, 2025). "Collectively, these findings suggest that docetaxel induces pyroptosis in prostate cancer cells, and GSDME overexpression shifts the balance from apoptosis to pyroptosis." (PMID 41413917, 2025). "Collectively, these findings demonstrated that XN triggered GSDME-mediated pyroptosis in prostate cancer cells through initiation of the mitochondrial intrinsic apoptosis pathway." (PMID 41226386, 2025). "In this study, we extended this conventional understanding by proposing that GSDME-dependent pyroptosis also contributed to XN’s anti-tumor effects in prostate cancer." (PMID 41226386, 2025). "To investigate the role of docetaxel and GSDME in prostate cancer, we conducted experiments focusing on their effects on cellular processes." (PMID 41413917, 2025). "During this process, the generated ROS activated Caspase‐3/gasdermin E (GSDME)‐dependent pyroptosis in RM‐1 prostate cancer cells, leading to the release of abundant DAMPs and pro‐inflammatory cytokines." (PMID 39494618, 2024). "Among various prostate cancer drugs, only docetaxel significantly elevated GSDME expression." (PMID 41413917, 2025). "To further clarify the physiological role of CDC20 in regulating cell death, we identified the gasdermin protein GSDME as a novel ubiquitin substrate of CDC20 in the prostate cancer setting, which offers further molecular insights into its regulation of anti-tumor immunity." (PMID 37528490, 2023). "Next, we sought to investigate whether the protein stability of GSDME was affected by the 26S proteasome pathway in prostate cancer." (PMID 37528490, 2023). "However, the molecular regulation of GSDME protein in prostate cancer remains elusive." (PMID 37528490, 2023). "In prostate cancer cells, this mutant showed reduced binding to SKP2 and decreased SKP2-mediated ubiquitination of GSDME." (PMID 41413917, 2025). "The results of single-cell sequencing suggest that GSDME can recruit CD8 + T lymphocytes and NK cells in prostate cancer." (PMID 41413917, 2025). "Our data indicated that CDC20, an E3 ligase highly overexpressed in both prostate cancer and CRPC, negatively regulated the pyroptosis pathway by targeting GSDME for ubiquitination-mediated proteolysis in a degron-dependent manner." (PMID 37528490, 2023). "To further examine this hypothesis in prostate cancer cell models, we found that PC3, NCIH660, VCAP, and 22RV1 expressed CDC20 and GSDME at high levels with dataset from CCLE." (PMID 37528490, 2023). "Furthermore, docetaxel induced pyroptosis in prostate cancer cells via the GSDME pathway, influencing the immune microenvironment without affecting cell viability." (PMID 41413917, 2025). "Importantly, the protein expression of GSDME, but not other pyroptosis executing gasdermins, was significantly decreased in prostate cancer." (PMID 37528490, 2023).
Ureteral obstruction (6 papers, 2021 to 2024). Obstruction of the flow of urine through the ureter. "Recently, researchers have observed that caspase-3/GSDME-mediated pyroptosis causes ureteral obstruction-induced renal tubule injury and diabetic nephropathy." (PMID 36052125, 2022). "Moreover, GSDME-mediated pyroptosis and inflammation initiate renal tubular injury caused by ureteral obstruction, which can lead to late progression of renal hydronephrosis, inflammation, and fibrosis." (PMID 38388468, 2024). "Moreover, GSDME-mediated pyroptosis serves as the initiation point of renal tubular injury in ureteral obstruction, which can lead to the late progression of hydronephrosis, inflammation, and fibrosis." (PMID 38388468, 2024).
acute kidney injury (5 papers, 2021 to 2026). Sudden and sustained deterioration of the kidney function characterized by decreased glomerular filtration rate, increased serum creatinine or oliguria. "Loss of GSDME effectively ameliorated cisplatin- or ischemia–reperfusion-induced inflammation and acute kidney injury by inhibiting caspase-3/GSDME-induced pyroptosis." (PMID 36920176, 2023). "The GSDME-deficient mice and human TECs were employed to prove that caspase-3/GSDME-triggered pyroptosis and inflammation contribute to acute kidney injury, and treatments targeting GSDME could be a new insight into DKD." (PMID 39000237, 2024). "Pyroptosis emerged via NLRP3 inflammasome activation and GSDMD/GSDME cleavage, exacerbating inflammation and overt renal failure." (PMID 41301789, 2025). "Their research also examined the role of GSDME in renal cellular pyroptosis and in the pathogenesis of cisplatin-induced acute kidney injury (AKI) in mice that received cisplatin." (PMID 34867412, 2021).
cervical cancer (5 papers, 2020 to 2022). A primary or metastatic malignant neoplasm involving the cervix. "constructed a new prognosis predication model based on 8 risk-related PRGs (GPX4, GSDME, GZMA, GZMB, IL1B, NOD1, PRKACA, and TNF) in cervical cancer, which had good predictive ability (AUC = 0.794)." (PMID 35912258, 2022). "Overexpression of GSDME in cervical cancer cell could result in Doxorubicin-induced apoptosis shifting into pyroptosis in a CASP3-dependent manner." (PMID 36071875, 2022).
diabetic nephropathy (5 papers, 2021 to 2025). "Recent studies have reported the involvement of both gasdermin E (GSDME) and caspase-3 in renal pyroptosis, including in diabetic nephropathy and obstructive nephropathy." (PMID 36052125, 2022). "Another recent study has shown that GSDME-mediated cell death may be involved in the development of diabetic nephropathy." (PMID 34746148, 2021).
influenza (5 papers, 2024 to 2025). An acute viral infection of the respiratory tract, occurring in isolated cases, in epidemics, or in pandemics; it is caused by serologically different strains of viruses (influenzaviruses) designated A, B, and C, has a 3-day incubation period, and usually lasts for 3 to 10 days. "Mice deficient in GSDME (Gsdme−/−) showed improved survival and greater influenza disease resistance compared to their wildtype littermate controls." (PMID 40481027, 2025). "In this study, we investigated a potential role for GSDME in promoting immunopathology during severe influenza infection." (PMID 40481027, 2025). "For instance, the caspase-3/GSDME pathway has been well-documented in alveolar epithelial cells during infections with other influenza subtypes including H1N1, H9N2, and H10N3." (PMID 41305513, 2025). "Influenza infection activates caspase-3, which cleaves GSDME, leading to pyroptosis and cytokine release." (PMID 39591329, 2024). "The influenza-induced activation of GSDME further exacerbates cell death and inflammation, highlighting the virus’s ability to exploit different forms of pyroptosis to its advantage." (PMID 39591329, 2024). "Together, these findings demonstrate a pivotal role for GSDME in severe influenza pathogenesis." (PMID 40481027, 2025). "Consequently, further work is required to establish the significance of GSDME activity in influenza pathogenesis." (PMID 40481027, 2025). "In this study, we investigated a role for GSDME in severe influenza." (PMID 40481027, 2025). "In addition to the established role of GSDMD in driving IAV pathogenesis, recent studies have investigated whether GSDME contributes similarly to influenza severity." (PMID 40766393, 2025). "Collectively, these studies point to the detrimental role of GSDMD- and GSDME-mediated pyroptosis in IAV infection and suggest that targeting GSDMD and/or GSDME may provide a novel therapeutic option for treating severe influenza infection." (PMID 41011440, 2025).
Sepsis (5 papers, 2022 to 2025). Sepsis is defined as life-threatening organ dysfunction caused by a dysregulated host response to infection. "Future research should further explore the specific mechanisms underlying the role of GSDME in sepsis-induced cardiomyopathy to assess its potential as a therapeutic target." (PMID 41550939, 2025). "Notably, during sepsis, the protein expression of GSDMA-NT, GSDMD-NT and GSDME-NT are reported to increase in sepsis-associated organ injuries, indicating that pyroptosis could play important roles in sepsis." (PMID 35967871, 2022). "GSDMD has been recognized as the primary substrate for Caspases in pyroptosis, particularly in sepsis, while GSDME mediates pyroptosis in other diseases." (PMID 37962578, 2024). "Among them, four classes are implicated in sepsis, including GSDMA, GSDMB, GSDMD and GSDME, with GSDMD being the most widely studied." (PMID 38022612, 2023). "GSDME activation is a critical and unique mechanism by which infection contributes to cytokine storm and lethality in sepsis." (PMID 38022612, 2023). "Although there is currently no direct evidence linking GSDME to sepsis-induced cardiomyopathy, existing studies have shown that GSDME plays a role in sepsis-associated damage to other organs, which may suggest the potential involvement of GSDME in sepsis-induced myocardial injury." (PMID 41550939, 2025). "This suggests that targeting the inhibition of GSDMD expression is not enough to suppress inflammation spread in sepsis models, and in future research, the GSDME-mediated pyroptosis pathway should not be ignored." (PMID 40520010, 2025).
skin melanoma (5 papers, 2018 to 2025). "Intrahepatic cholangiocarcinoma, cutaneous melanoma, uterine endometrioid carcinoma and uterine mixed endometrial carcinoma had the highest GSDMA (6.67%), GSDMB (2.7%), GSDME (6.52%) and PJVK (4.76%) mutation frequency, respectively." (PMID 35164740, 2022).
ZIKV infection (5 papers, 2022 to 2025). "Collectively, these results indicate that the ZIKV-GSDME-mediated pyroptosis is more likely to occur in those cells that are susceptible to ZIKV infection, and with relatively higher GSDME abundance." (PMID 35972780, 2022). "By establishing a mouse model of ZIKV infection, we further showed that the deletion of GSDME leads to the reduction of placental damage and associated adverse fetal outcomes in infected pregnant mice." (PMID 35972780, 2022). "Furthermore, the Western blot assay demonstrated that the ZIKV UTRs caused the activation of GSDME via the same signaling pathway as induced by ZIKV infection." (PMID 35972780, 2022). "The deletion of RIG-I significantly inhibited the LDH release and the activation of GSDME, as well as its upstream caspase-3 and caspase-8 during ZIKV infection, while the KO of MDA5 or MAVS only slightly suppressed this process." (PMID 35972780, 2022). "Zika virus (ZIKV) infection of pregnant immunocompetent wild-type (WT) C57BL/6N mice results in gasdermin E (GSDME)-mediated placental pyroptosis and congenital ZIKV syndrome (CZS)." (PMID 35972780, 2022). "Consistent with our previous observations in JEG-3 cells, the upregulation of RIG-I caused by ZIKV infection was also seen in MTC, and inhibition of either caspase-3 or caspase-8 prominently blocked ZIKV-induced activation of GSDME." (PMID 35972780, 2022). "Here, we report that ZIKV infection activates caspase-3 via the caspase-8-mediated extrinsic apoptotic pathway, which in turn activates GSDME to induce the pyroptosis of placental trophoblasts." (PMID 35972780, 2022). "Additionally, we found that overexpression of A20 upregulated cell death, as evidenced by increased CASP3-p17 and GSDME-p34 levels compared to wild-type cells during ZIKV infection." (PMID 39976465, 2025). "In this study, we identified a novel mechanism by which ZIKV infection induces the GSDME-mediated pyroptosis of placental cells and demonstrated that the KO of GSDME could alleviate the adverse fetal outcomes in ZIKV-infected mice." (PMID 35972780, 2022). "However, the engagement of intrinsic and/or extrinsic pathways to regulate the GSDME-dependent pyroptosis during ZIKV infection remains to be studied." (PMID 35972780, 2022). "Zika virus (ZIKV) infection induces the gasdermin E (GSDME)-mediated pyroptosis in JEG-3 cells." (PMID 35972780, 2022). "Before the in vivo experiments, mouse primary trophoblast cells (MTCs) from C57BL/6N mice at embryonic day 9.5 (E9.5) of pregnancy were isolated and cultured to investigate whether ZIKV infection could also induce the GSDME-mediated pyroptosis in mouse trophoblast cells." (PMID 35972780, 2022). "GSDME has also been shown to significantly contribute to lytic cell death upon influenza A virus (IAV) infection, EV71 infection, and Zika virus infection." (PMID 38932190, 2024). "It was observed that Huh-7 and A549 cells showed distinct pyroptotic cell death, elevated LDH levels, and GSDME cleavage upon ZIKV infection, whereas HeLa, HEK-293T, and SH-SY5Y cells exhibited no obvious cytopathic effects even at 72 hr post-infection." (PMID 35972780, 2022). "Although the deletion of gasdermin E (GSDME) does not impact the development or immune system of mice, it has been observed that pyroptosis by activating GSDME affects the innate immune system and leads to placental damage during ZIKV infection." (PMID 38409106, 2024). "Since there is no previous study reporting that ZIKV can induce GSDME-mediated pyroptosis, we asked whether it is a common cellular process during ZIKV infection." (PMID 35972780, 2022). "Interestingly, we found that KO of MAVS, a downstream molecule of RIG-I, only slightly reduced the cleavage of GSDME, which indicates the possibility that ZIKV infection leads to the placental pyroptosis via the non-canonical RIG-I pathway." (PMID 35972780, 2022).
ZIKV infection (continued). "We demonstrated that ZIKV infection could induce placental pyroptosis through the recognition of the viral genome by RIG-I followed by TNF-α release, which activates the caspase-8- and caspase-3-mediated cleavage of pyroptosis executor GSDME in placental cells." (PMID 35972780, 2022). "ZIKV infection of engineered or wild-type (WT) cells revealed that the KD of RIG-I, but not TLR7 and TLR8, conspicuously attenuated the ZIKV-induced pyroptotic cell death and GSDME cleavage, suggesting that RIG-I may play a major role in ZIKV-induced pyroptosis." (PMID 35972780, 2022).
age-related hearing loss (4 papers, 2015 to 2023). "Both the GSDME-mediated and classical pyroptotic pathways have been implicated in presbycusis." (PMID 36755014, 2023). "GSDME activation and consequent cochlear hair cell pyroptosis and inflammation may be important in the pathogenesis of presbycusis." (PMID 36755014, 2023).
cholangiocarcinoma (4 papers, 2021 to 2025). A carcinoma that arises from the intrahepatic biliary tree (intrahepatic cholangiocarcinoma) or from the junction, or adjacent to the junction, of the right and left hepatic ducts (hilar cholangiocarcinoma). "Furthermore, MTX–TMPs triggered cholangiocarcinoma cell pyroptosis via the gasdermin E (GSDME)-dependent pathway." (PMID 40429976, 2025).
esophageal cancer (4 papers, 2021 to 2022). A primary or metastatic malignant neoplasm involving the esophagus. "Some studies have found that high expression of GSDME in esophageal cancer causes cells to undergo pyroptosis." (PMID 36090967, 2022). "In esophageal cancer cells with high GSDME expression, neobractatin induces pyroptosis through the caspase-3/GSDME pathway." (PMID 36091247, 2022).
inflammatory bowel disease (4 papers, 2022 to 2023). A spectrum of small and large bowel inflammatory diseases of unknown etiology. "GSDME-mediated pyroptosis was suggested as a mechanism in periodontonitis, rheumatoid arthritis and inflammatory bowel diseases, which are more frequent in psoriatic patients." (PMID 37681881, 2023). "GSDME expression is significantly increased in the epithelial cells of the colonic mucosa of patients with inflammatory bowel diseases (IBD) compared to healthy humans." (PMID 35896522, 2022). "In this review, we discuss the impact of pyroptosis on inflammatory bowel disease (IBD), with a focus on the executive proteins of pyroptosis (GSDMB, GADMD, and GSDME) and IBD-related endogenous damage-associated molecular patterns (DAMPs) produced by pyroptosis." (PMID 35677444, 2022).
lung squamous cell carcinoma (4 papers, 2021 to 2025). "In lung squamous cell carcinoma, gasdermin E (GSDME) interacts with YBX1, facilitating its transport to the nucleus, where it directly promotes mucin expression." (PMID 40799245, 2025).